PTBP1 (polypyrimidine tract binding protein 1)
Diseases named in the same sentence as PTBP1 in open-access papers (continued):
Sharing a sentence is not in itself a finding about the gene and the disease.
cancer (continued). "Given the link between senescence and cancer, and given that insights into how PTBP1-related alternative splicing events modulate senescence in LUAD are currently limited, here, we consider whether the regulation of PTBP1 could influence senescence in LUAD patients." (PMID 39057099, 2024). "However, the current context of PTBP1's role with various types of non‐coding RNAs is not clear, and studying the physiological basis affecting PTBP1's role with non‐coding RNAs may be the key to deciphering how non‐coding RNAs function in cancer." (PMID 40579921, 2025). "PTBP1 could be quantified in all samples, ranging from 2.7–21.2 fmol/3 μg in the tumor samples (median 12.7 ± 7.2 fmol/3 μg) and 3.7–9.1 fmol/3 μg in the controls (median 7.4 ± 2.4 fmol/3 μg), showing no clear trend of regulation between cancer and control tissue." (PMID 31805664, 2019). "We also provide lines of evidence to support that the negative correlation between PTBP1 and exon skipping of NDUFV3 exists in other cellular senescence models and diverse cancers, indicating the universality of such splicing regulation mechanism and functional regulatory relationship." (PMID 39872664, 2024). "Given that PTBP1 may destabilize AXL mRNA, it would be interesting to investigate, in cells expressing no or little PTBP1, whether AXL inhibitors may effectively inhibit cancer cells growth because of the potential likelihood of their AXL-dependency." (PMID 31729427, 2019). "Additional studies are necessary to uncover the precise role of PTBP1 in H2O2–mediated cytotoxicity and determine if the lack of PTBP1 degradation in response to a treatment with oxidants may serve as a marker for resistance to oxidative stress in individual cancer cell lines." (PMID 22911749, 2012).
tumor (120 papers, 2011 to 2026). "The CAPZA1[T] variant binds hnRNP K and PTBP1 to stabilize its mRNA and inhibit tumor aggressiveness, whereas the CAPZA1[G] allele promotes UPF1-mediated mRNA decay and diminishes this protective effect." (PMID 41787560, 2026). "It was found that in tumour cells, knockdown of PTBP1 caused MCL1 mRNA to accumulate in the cytoplasm in addition to increasing MCL1 mRNA levels, upregulating the cytoplasmic/nuclear ratio, but not decreasing the amount of mRNA in the nucleus." (PMID 40579921, 2025). "Polypyrimidine tract binding protein 1 (PTBP1) is an RNA-binding protein implicated in various types of tumor development and metastasis." (PMID 38247832, 2024). "In summary, our analysis suggests that PTBP1 upregulation is linked to the activation of mismatch repair-related mechanisms and increased methylation modification activity in tumor tissues." (PMID 38918441, 2024). "Tumour mutational burden was significantly and positively correlated with PTBP1 expression in ACC, LGG, STAD, MESO, SARC, PAAD, UCEC and LUAD." (PMID 38918441, 2024). "The growth of vector PC‐3 tumors was significantly attenuated after IR treatment, whereas PTBP1 OE resulted in a greater rate of tumor growth than control, causing a less pronounced reduction in xenograft volume and weight post‐IR." (PMID 39287090, 2024). "Down-regulation of PTBP1 was also associated with suppressed inflammatory secretome in tumor cells via modulation of intracellular trafficking genes, but its effect in adipose tissue remains elusive." (PMID 35776773, 2022). "Collectively, these data demonstrate that PTBP1-mediated exon skipping events, which generate splice products closely associated with poor differentiation and tumor progression, can be efficiently attenuated by SON knockdown." (PMID 34548489, 2021). "As other examples, PTBP1 RNA binding protein that associated with tumor metastasis in CRC tissues directly interacts with autophagy gene ATG10 and regulates ATG10 expression level." (PMID 32265986, 2020). "Knocking down PTBP1 prevented tumor growth caused by the presence of senescent cells in two tumor models." (PMID 29990503, 2018). "PTBP1 was previously reported as a key player in alternative splicing of many genes associated to lineage-specific cell differentiation or tumor genesis, such as cell cycle." (PMID 25079003, 2014). "Moreover, this study linked two well-established tumor drivers, PTBP1 and SLC7A11, through the post-transcriptional regulation of SLC7A11 by PTBP1." (PMID 41313521, 2025). "We then aimed to elucidate the molecular mechanism underlying the anti-tumor effects of si-PTBP1." (PMID 39153986, 2024). "Notably, we also found a USF1-downstream gene PTBP1, which had been linked to the immune evasion of tumor cell in TNBC." (PMID 37900187, 2023). "Moreover, the depletion of PTBP1-caused tumour regression was significantly compromised by exogenous c-Myc expression." (PMID 36635500, 2023). "Elucidation of the role of PTBP1 in the AXL-related malignant phenotypes may provide new molecular insights into the mechanisms underlying tumor progression and hopefully lead to new potential therapeutic modalities." (PMID 31729427, 2019). "Knockdown of either PTBP1 or SRp20 caused substantial growth inhibition or apoptosis, indicating a requirement for their overexpression to maintain the transformation properties of tumor cells." (PMID 26336992, 2015). "Moreover, we found both USF1 and PTBP1 expression were significantly associated with the infiltration levels of CD4+ Th1 cells that could function in pro-tumor immunity." (PMID 37900187, 2023). "Biotin-RNA pulldown combined with mass spectrometry and RIP assays showed that CAPZA1[T] mRNA binds to hnRNP K and PTBP1, enhancing its stability and tumor-suppressive function." (PMID 41787560, 2026). "The upregulation of PTBP1 expression is related to the proliferation and migration of various tumors, and glycolysis is the most important mechanism in tumor progression." (PMID 40051638, 2025).
tumor (continued). "PTBP1-depleted cells (shPTBP1-2) were implanted subcutaneously into hairless mice, and tumor growth was monitored over time." (PMID 40296916, 2025). "In this study, PTBP1 knockout inhibited EBC1 tumor growth in vivo, providing a foundation for developing PTBP1 inhibitors for NSCLC treatment." (PMID 40790019, 2025). "Cell-derived xenograft assays demonstrated that PTBP1 knockdown significantly suppressed tumor growth in vivo." (PMID 41313521, 2025). "By gaining a deeper understanding of the specific roles of PTBP1 in different tumour types, tumour biology can be better understood, thus promoting the development of precision‐targeted medicine." (PMID 40579921, 2025). "Studies have found that among 30 tumour types, the positive correlation between PTBP1 expression and LAG3 and PD‐1 expression is the most common." (PMID 40579921, 2025). "Future studies are needed to confirm that the tumor-suppressive effect of PTBP1 depletion in EC is, at least partially, dependent on SLC7A11 downregulation." (PMID 41313521, 2025). "For instance, PTBP1 regulates key gene expression via alternative splicing, influencing processes such as tumor proliferation, migration, invasion, and apoptosis." (PMID 41313521, 2025). "Studies have shown that many non‐coding RNAs can bind to PTBP1 to influence the Warburg effect to affect tumour energy metabolism." (PMID 40579921, 2025). "Analysis of CPTAC data revealed that PTBP1 protein levels were significantly elevated in advanced tumor stages (Stage 1–2) compared to normal tissues." (PMID 41313521, 2025). "Stress‐induced tDDX3X‐C facilitates tumor adaptation through loss‐of‐function PRDM2 splicing, while PTBP1 rewires metabolism and signaling via CERS5 and MPZL1 isoform switching." (PMID 41399527, 2025). "Decoy oligonucleotides targeting PTBP1, when introduced into cells, are able to accurately and directly bind to each other and to the PTBP1 protein, interrupting its binding to hnRNA and thus inhibiting the role of PTBP1 in tumours." (PMID 40579921, 2025). "It aims to provide a theoretical basis for basic research on the role of PTBP1 in tumours and clinical targeting therapies." (PMID 40579921, 2025). "In IDH-WT GBM, the repression of CDC42-N splicing by PTBP1 ensures the maintenance of actin dynamics required for tumor progression and cell survival." (PMID 39915450, 2025). "PTBP1, one of the most important AS-related RBPs, is overexpressed and promotes tumor cell proliferation and angiogenesis in GBM." (PMID 38302461, 2024). "Our results showed that silencing PTBP1 alone significantly reduced tumor growth rate and size compared with the control group." (PMID 39153986, 2024). "Future studies will evaluate the potential role of PTBP1 in the influence of the tumor-promoting aspects of SASP in LUAD." (PMID 39057099, 2024). "PTBP1 expression was found to be positively correlated with tumour neo-antigens in patients with LGG, UCEC and STAD." (PMID 38918441, 2024). "A recent study reported that the long noncoding RNA FIRRE acts as a tumor promoter by interacting with PTBP1 to stabilize BECN1 mRNA and facilitate autophagy." (PMID 39156764, 2024). "PTBP1, also known as hnRNPL, is mainly involved in the regulation of gene transcription, mediating the regulation of alternative splicing events in tumor invasion-related genes." (PMID 38071681, 2024). "Further analysis of ASO-treated tumor xenografts showed effective downregulation of PTBP1 expression and induction of apoptosis in PTBP1-ASO group." (PMID 38662454, 2024). "We found that as tumour malignancy increased, the expression of PTBP1 likewise increased significantly." (PMID 38918441, 2024). "During the investigation of CRC, PTBP1 was found to have a regulatory function in tumor cell invasion and facilitate the Warburg effect in CRC16,17." (PMID 38273088, 2024).
tumor (continued). "One potential reason for these discrepancies is the distinct PTBP1‐governed AS networks among different tumor types." (PMID 39287090, 2024). "Immunohistochemical results of xenograft tumor showed that PTBP1 knockdown increased LC3B and P62 expression, suggesting autophagic flux blockade." (PMID 39153986, 2024). "To further investigate the role of PTBP1 in GC, we initially verified the upregulation of PTBP1 mRNA and protein levels in more GC tumor tissues through RT–qPCR and western blot analysis." (PMID 39153986, 2024). "Herein, PTBP1 was found to be markedly upregulated in malignant OC tumor tissues, implying a potential oncogenic function of PTBP1 in OC." (PMID 38071681, 2024). "miR-1 and miR-133 also function as anti-tumor non-coding RNAs expressed in muscle tissues, which mediate cell autophagy by silencing PTBP1." (PMID 38785973, 2024). "Subsequently, we confirmed the upregulation of PTBP1 protein in GC tumor tissues via Western blot analysis." (PMID 38247832, 2024). "Both chloroquine and PTBP1 silencing alone reduced tumor growth rate and volume compared with the control." (PMID 39153986, 2024). "The positive associations observed between PTBP1 and tumor immune features within LGG cohorts indicate its potential role in modulating the tumor microenvironment." (PMID 38918441, 2024). "In this study, we demonstrated that PTBP1 knockdown significantly inhibited GC cell viability and tumor growth, both in vitro and in vivo." (PMID 39153986, 2024). "Unexpectedly, certain circRNAs were observed to perform novel functions to stabilise or decrease the expression of RBPs including human antigen R (HuR) and polypyrimidine tract-binding protein 1 (PTBP1) which are involved in tumour progression." (PMID 38341427, 2024). "Herein, the levels of HCP5 and PTBP1 were found to be markedly increased in malignant OC tumor tissues and OC cell lines." (PMID 38071681, 2024). "The Spearman correlation coefficient between PTBP1 gene expression and tumor neo-antigen counts was calculated." (PMID 38918441, 2024). "Impressively, the combination of chloroquine and PTBP1 silencing significantly enhanced the antitumor effect, exhibiting the slowest tumor growth rate and the smallest tumor volume." (PMID 39153986, 2024). "PTBP1 expression was positively correlated with tumor neo-antigen counts in LGG, UCEC, and STAD, while it exhibited a negative correlation in THCA." (PMID 38918441, 2024). "In this study, we have validated that interference with PTBP1 significantly impairs the viability of GC cells and curtails tumor growth, both in vitro and in vivo." (PMID 39153986, 2024). "Collectively, these results further support the notion that PTBP1 is a tumour promoter of GC cells both in vitro and in vivo." (PMID 36635500, 2023). "Through the alternative splicing of exons, PTBP1 is involved in tumour EMT, glycolysis and metabolic reprogramming." (PMID 36635500, 2023). "It was also found that the RNA-binding proteins hnRNPA1 and PTBP1/2, which are highly expressed in tumours, play a role in exon IIIc skipping." (PMID 38002944, 2023). "Classical therapeutic targets of tumours involved in PTBP1 include HER2, STAT3 etc., and inhibitors against these targets have been developed." (PMID 36635500, 2023). "The relationship between PTBP1 and tumor metabolism is mainly the ability to regulate the expression of PKM2 and promote glycolysis." (PMID 36635270, 2023). "Animal Living Imaging System showed that the tumor fluorescence intensity of PTBP1 Cas9-KO group was weaker than that of WT group." (PMID 37670313, 2023). "In the present study, we showed that PTBP1 can promote the proliferation of GC cells in vitro and accelerate the growth of tumours in vivo." (PMID 36635500, 2023). "Polypyrimidine tract binding protein 1 (PTBP1) was shown to be involved in the development of embryonic stem cells and is now being considered as a therapeutic target for tumour progression and stem-cell characteristics." (PMID 36635500, 2023).
tumor (continued). "Taken together, these findings confirmed that miR-195-5p acted as a tumor suppressor by modulating PTBP1 in LUAD." (PMID 35600383, 2022). "And total RNA was extracted from xenograft tumor tissues to detect the effect of silencing PTBP1 on the expression of ITSN1-S and ITSN1-L." (PMID 36171198, 2022). "We integrated tumor and normal samples from TCGA databases to identify PTBP1 mRNA expression characteristics." (PMID 36595978, 2022). "Among PTBPs, PTBP1 showed the highest RNA expression level in tumor tissues, followed by PTBP3; the expression level of PTBP2 was the lowest among the three genes." (PMID 36203873, 2022). "In conclusion, TINCR can promote LCSC self-renewal and tumor progression by autophagy activation through PTBP1/ATG5 regulatory pathway." (PMID 36385098, 2022). "Considering that SFTA1P and PTBP1 share the same tumor-promoting effect, we focused on genes that were simultaneously up- or down-regulated in SFTA1P RNA-seq and PTBP1 RNA-seq experiments." (PMID 36344495, 2022). "The combined anti-tumor effects of PTBP1 inhibition plus 5-Fu treatments will be verified using in vitro and in vivo models." (PMID 36447254, 2022). "After including the normal tissues of the GTEx dataset as controls, we further evaluated the difference in PTBP1 expression between normal and tumor tissues." (PMID 36595978, 2022). "In our study, PTBP1 was overexpressed in the majority of tumor tissues compared to that in normal tissues." (PMID 36595978, 2022). "In vivo, U87 growth generated xenografts was substantially shrank due to PTBP1 knockdown induced neural differentiation, and these tumor-bearing mice had a prolonged survival time." (PMID 35664063, 2022). "Our findings demonstrate that SFTA1P can promote tumor progression by mediating the degradation of TPM4 mRNA through its interaction with PTBP1 protein." (PMID 36344495, 2022). "While silencing of ITSN1-L followed PTBP1 knockdown (shPTBP1/shITSN1-L/LN229) produced a statistically significant increase in the tumor invasion frequency compared to the control group." (PMID 36171198, 2022). "In the 30 tumor types, PTBP1 expression had the most prevalent positive correlation with LAG3 and PD-1 expression." (PMID 36203873, 2022). "Recent studies suggested that CD154 has anti-tumor activity and growth-inhibitory effects and that PTBP1 plays a crucial role in stabilizing CD154 mRNA." (PMID 35600383, 2022). "We used the GEPIA2 tool to combine all tumor expression data from TCGA and acquired the top 100 genes that were correlated with the expression of PTBP1." (PMID 36595978, 2022). "In support to our prediction, we observed significant upregulation of PTBP1 expression in tumor samples compared to normal (p = 0.0467) and it showed significant positive correlation with EGFR-A isoform (r = 0.7404, p < 0.0001)." (PMID 33888812, 2021). "ST7-AS1 binds and inhibits polypyrimidine tract-binding protein 1 (PTBP1), thus suppressing the Wnt/β-catenin signaling and leading to an increase in the tumor progression." (PMID 35004666, 2021). "SGO1-AS1 knockdown increased tumor spheroid formation and the ALDH1+ population, whereas loss of PTBP1 or treatment with SB431542 significantly abolished these effects." (PMID 34706749, 2021). "The nude mice injected with U2OS cells in the presence of PTBP1 exhibited an elevated tumor volume, while the results in nude mice injected with U2OS cells in the absence of PTBP1 were opposite (p < 0.05)." (PMID 33621196, 2021). "In contrast, cisplatin treatment combined with PTBP1 knock‐down induced apoptosis in large areas of tumours." (PMID 32207235, 2020). "For example, upregulation of PTBP1 in tumor cells affected glycolytic metabolism by promoting AS of the PKM2 variant, leading to acquisition of drug resistance to chemotherapy." (PMID 32655719, 2020).